DPP4 (dipeptidyl peptidase 4)
Diseases named in the same sentence as DPP4 in open-access papers (continued):
Sharing a sentence is not in itself a finding about the gene and the disease.
diabetes (continued). "From a therapeutic perspective, dipeptidyl peptidase 4 (DPP- 4), an enzyme responsible for degrading GLP-1, is a significant target in diabetes treatment." (PMID 41155553, 2025). "Major clinical trials of SGLT2 inhibitors, GLP-1 receptor agonists, DPP-4 inhibitors, and RAAS inhibitors in patients with diabetes, diabetic cardiomyopathy, and COVID-19: Cardiovascular and metabolic outcomes." (PMID 41158128, 2025). "Among the most common diabetes mellitus medications, metformin stands out with prescription to 80% of patients, followed by the group comprising SGLT-2 inhibitors (19%), DPP-4 inhibitors (14%), GLP-1 RA (7%) and insulin (8%)." (PMID 39946340, 2025). "Vildagliptin, a dipeptidyl peptidase-4 inhibitor (DPP-4i), is used to treat type 2 diabetes mellitus (DM2) because it increases the concentrations of incretins, which stimulate the release of insulin and reduce glucagon secretion in a glucose-dependent manner." (PMID 40498942, 2025). "Particularly since 2009, the introduction of dipeptidyl peptidase-4 (DPP-4) inhibitors and glucagon-like peptide-1 (GLP-1) receptor agonists (RAs) has significantly transformed diabetes care in Japan." (PMID 40607140, 2025). "Recent advancements in T2DM treatment, including new DPP-4 inhibitors, oral small-molecule GLP1-RAs, and newer options for SGLT2i, have shown promise in improving diabetes management." (PMID 40149950, 2025). "The emergence of diabetes accompanied by metabolic dysregulation following SARS-CoV-2 infection, along with the involvement of DPP4 in both SARS-CoV-2 infection and T2D, indicates common underlying pathological mechanisms." (PMID 40431631, 2025). "New pharmacological agents, including sodium-glucose co-transporter type 3 (SGLT-2) inhibitors, dipeptidyl peptidase-4 (DPP4) inhibitors, and glucagon-like peptide-1 receptor agonist (GLP-1 RA) may have effects beyond glycemic control pertinent to cardiovascular risk reduction in diabetes." (PMID 40260277, 2025). "Linagliptin, a dipeptidyl peptidase-4 (DPP-4) enzyme inhibitor, is a great alternative when contemplating medications for people with Type 2 diabetes mellitus." (PMID 40225279, 2025). "Emerging combination therapies targeting different pathophysiologic mechanisms of type 2 diabetes mellitus (T2DM), such as SGLT2 inhibitors and DPP-4 inhibitors, offer promise in reducing GV." (PMID 41291962, 2025). "Moreover, intervention studies showed that combination therapy based on the concomitant use of vitamin D and DPP-4 inhibitors (VIDPP-4i) may preserve beta-cell function in patients with type 1 diabetes mellitus (T1D) and latent autoimmune diabetes in adults (LADA)." (PMID 40843763, 2025). "It remains to be determined what the specific effects of newer agents in the treatment of diabetes and obesity, such as GLP-1 agonists and DPP-4 inhibitors, are on vascular aging." (PMID 39456971, 2024). "We utilized a combination of Medical Subject Headings (MeSH) terms and keywords such as "Type 2 Diabetes Mellitus", "SGLT2 inhibitors", "DPP-4 inhibitors", "Metformin", "Insulin", and "combination therapy"." (PMID 39723311, 2024). "Therefore, another objective of this study was to confirm whether the incretin secretion capacity, which is essential for the action of DPP4-inhibitors, is preserved in patients with DM1, and to evaluate the effect of DPP-4 inhibitors in patients with DM1 complicated by diabetes using CGM." (PMID 39274465, 2024). "Biguanides, DPP-4 inhibitors, GLP-1 agonists, Insulin, and SGLT-2 inhibitors are the most common diabetes medications." (PMID 39759947, 2024). "In the realm of clinical diabetes management, GLP‐1R antagonists and DPP‐4 inhibitors are prescribed medications aimed at stimulating the GLP‐1R signalling pathway." (PMID 38926763, 2024).
diabetes (continued). "several classes of drugs are known for the treatment of diabetes such as Exenatide as glucagon-like peptide 1 (GLP 1) mimetic agents, Gliptins as dipeptidyl peptidase 4 (DPP4) inhibitors, Glitazones as peroxisome receptor antagonists." (PMID 38565703, 2024). "Overall, the clinical importance of DPP-4 as a target lies in its involvement in glucose homeostasis and the potential therapeutic applications of DPP-4 inhibitors in diabetes and other related diseases." (PMID 38792165, 2024). "As research continues to explore DPP-4 inhibitors and combination therapies, TECOS remains a foundational study in understanding the cardiovascular implications of diabetes medications." (PMID 39768866, 2024). "Given the shared neuropathophysiological traits between AD and type 2 diabetes mellitus (T2DM), repurposing antidiabetic medications, such as dipeptidyl peptidase 4 inhibitors (DPP4i), has emerged as a promising therapeutic strategy." (PMID 39610591, 2024). "Metformin, dipeptidyl peptidase-4 (DPP-4) inhibitors, and sodium-glucose transport protein-2 (SGLT-2) inhibitors, which are widely used diabetes treatments, have various effects, including anti-inflammatory properties that impact a range of conditions." (PMID 39333866, 2024). "Incretin-based therapies such as DPP-4 inhibitors and GLP-1 agonists should also be prioritized in diabetes management in these patients, possibly adjusting patients’ diabetes regimen to include either class." (PMID 39598137, 2024). "The incretin-based drugs glucagon-like peptide 1 (GLP-1) receptor agonists and dipeptidyl peptidase-4 (DPP-4) inhibitors, such as sitagliptin, are both used as glucose-lowering therapy for type 2 diabetes mellitus." (PMID 39271520, 2024). "Of note, compared with the Diabetes specialist clinics, use of SGLT2 inhibitors (13.2% versus 43.2%), GLP1-RAs (1.0% versus 6.2%), DPP4 inhibitors (15.4% versus 47.9%), and insulin (27.7% versus 58.1%) were lower in the General medicine clinics." (PMID 38166049, 2024). "Therefore, the administration of DPP-4 inhibitors to patients with diabetes and COVID-19 could have a meaningful role in the prevention of long-term complications of COVID-19 through their well-i dentified anti-fibrotic, anti-i nflammatory, cardioprotective and nephroprotective actions." (PMID 39526061, 2024). "Dipeptidyl peptidase 4 (DPP4) inhibitors, commonly known as gliptins, have been an integral part of the treatment of type 2 diabetes mellitus (T2DM) for several years." (PMID 38002032, 2023). "In this cohort study, patients with type 2 diabetes mellitus and eGFR < 30 mL/min per 1.73 m2 with a first prescription for GLP-1RAs or dipeptidyl peptidase 4 inhibitors (DPP-4is) from 2012 to 2021 (n = 125,392) were enrolled." (PMID 36932379, 2023). "The major conventional hypoglycemic drugs used for the treatment of diabetes include diguanides, sulphonylureas, SGLT2 inhibitors, DPP-4 inhibitors, GLP-1 receptor agonists, alpha glucosidase inhibitors, and thiazolidinediones (TZDs), etc.." (PMID 38179301, 2023). "Dipeptidyl peptidase-4 (DPP4) deactivates incretin hormones, whereas DPP4 inhibitors, such as sitagliptin, block this degradation, increase the incretin levels, and prolong insulin secretion; therefore, sitagliptin could be a potential therapeutic for type 2 diabetes mellitus." (PMID 37047505, 2023). "DPP‐4, the enzyme that converts PYY1‐36 to PYY3‐36, is thought to be a mediator of the link between obesity and diabetes by inactivating incretins such as GLP‐1, and regulating inflammation and insulin resistance in the liver and adipose tissue." (PMID 36345253, 2023). "This study sees the potential of 2657 Filipino phytochemicals as a source of natural inhibitors against four targets of diabetes: PTP1B, DPP-4, SGLT-2, and FBPase." (PMID 37513175, 2023).
diabetes (continued). "The peptidase activity of CD26/DPP4 exerts effects on multiple proteins, including incretin hormones, and has led to the development of CD26/DPP4 inhibitors as therapeutic agents for diabetes." (PMID 36949656, 2023). "In the early 2000s in Pakistan, DPP-4 inhibitors and recently a newer class of drug, i.e., SGLT-2 inhibitor, have been introduced with cost-effective benefits for diabetes management." (PMID 36060955, 2022). "Type 2 diabetes mellitus (T2DM) is a growing global public health issue, and dipeptidyl peptidase-4 (DPP-4) is a potential therapeutic target in T2DM." (PMID 36250007, 2022). "Serum DPP4 activity was found to increase in patients with T1DM and the elevation is correlated with duration of diabetes." (PMID 35309368, 2022). "Gliptins, a novel class of antidiabetics, are dipeptidyl peptidase-4 inhibitors (DPI-4) for improving β-cell health and controlling blood glucose levels in diabetes mellitus type 2." (PMID 35625906, 2022). "Recently, brain derived neurotrophic factor (BDNF), dipeptidyl peptidase-4 (DPP4), and Ca2+ brain dysregulation were identified as novel biomarkers and potential therapeutic targets for diabetes-related cognitive impairment." (PMID 35958117, 2022). "Lastly, a study using insulin resistant-HepG2 cell model, reported that spirulina protein had anti-diabetes effects in insulin resistant cell models, with 11 anti-diabetes peptides being identified, and LRSELAAWSR displaying the best activities on DPP-4." (PMID 36557218, 2022). "In people with Type 2 diabetes mellitus fasting during Ramadan, use of SGLT-2 inhibitors combined with metformin is as safe, effective and well-tolerated as DPP4 inhibitors combined with metformin." (PMID 36224542, 2022). "Incident type 2 diabetes mellitus (T2DM) patients and propensity score matched T2DM SGLT2i and Dipeptidyl peptidase 4 inhibitor (DPP4i) users were investigated." (PMID 35710921, 2022). "Dipeptidyl peptidase-4 inhibitors (DPP-4I), key regulators of the actions of incretin hormones, exert anti-hyperglycemic effects in type 2 diabetes mellitus (T2DM) patients." (PMID 36072931, 2022). "This study will use all the available IPD and aggregate-level trial data and data from a diabetes register to estimate the effectiveness of SGLT2 inhibitor, GLP1 receptor analogue and DPP4 inhibitors for patients in routine care settings." (PMID 36302574, 2022). "Effect of other T2DM medications (SGLT2 inhibitors, dipeptidyl peptidase-4 inhibitors, GLP-1 agonists) on LUTD in diabetes remains to be studied." (PMID 35545721, 2022). "Investigating whether dipeptidyl peptidase-4 inhibitors (DPP4i) could influence the progression of type B intramural hematoma (IMHB) in patients with diabetes mellitus (DM)." (PMID 36330007, 2022). "When combined with metformin, the DPP-4 inhibitor (vildagliptin) and the SGLT2 inhibitor (empagliflozin) have a significant beneficial effect on diabetes management and play a vital role in lowering body weight and maintaining the lipid profile." (PMID 36060955, 2022). "Due to the ability of DPP-4 to cleave the GLP-1 hormone, inhibitors that potentiate the effects of the incretin hormones were explored for the treatment and management of diabetes." (PMID 36547924, 2022). "For uncontrolled diabetes mellitus patients, SGLT-2 inhibitors, DPP-4 inhibitors, and GLP-1 receptor agonists are regarded as first-line add-on medications to maintain glycemic control." (PMID 36060955, 2022). "DPP4 inhibitor, as a hypoglycemic agent, was approved by the Food and Drug Administration (FDA) for the treatment of type 2 diabetes mellitus (T2DM)." (PMID 34955820, 2021). "Dipeptidyl peptidase-4 (DPP-4) inhibitors and sodium glucose cotransporter-2 (SGLT-2) inhibitors, oral drugs for the treatment of patients with type 2 diabetes mellitus (T2D), are mainly used to control blood glucose." (PMID 33995063, 2021).
diabetes (continued). "Further larger trials should also be done to confirm these results and especially other diabetes drugs including SGLT2 inhibitors and DPP-4 inhibitors." (PMID 34603199, 2021). "Knowledge of the previously established roles in DPP-4 inhibition and partial reversal of STZ-induced diabetes have been expanded upon." (PMID 34081167, 2021). "We previously reported that the topical administration (eye drops) of sitagliptin, a dipeptidyl peptidase-4 (DPP-4) inhibitor, prevented retinal neurodegeneration induced by diabetes in db/db mice." (PMID 34944588, 2021). "The data in this study clearly suggest that it would be favorable to start combination therapy of DPP-4 inhibitor and SGLT2 inhibitor in an early phase of diabetes in order to efficiently preserve β-cell mass and function." (PMID 34373487, 2021). "As DPP4 is known to inactivate the incretin glucagon-like peptide-1 (GLP-1), the discovery of new DPP4 inhibitors is considered an indirect approach to increase GLP-1 levels and thus to manage diabetes mellitus type 2." (PMID 34373963, 2021). "Recent studies also indicate that DPP4 and DPP7 directly link between periodontal and systemic diseases, such as type 2 diabetes mellitus and coagulation abnormality, respectively." (PMID 33006264, 2021). "Dipeptidyl peptidase-4 inhibitors prolong the bioavailability of the endogenously secreted GLP-1, thereby exerting a beneficial therapeutic effect on diabetes." (PMID 33928135, 2021). "Patients with diabetes were treated with metformin (MTF) and/or inhibitors of dipeptidyl peptidase 4 (DPP4i) and/or sodium-glucose cotransporter-2 inhibitors (SGLT2i); no treatment had been given on the day of admission." (PMID 33466617, 2021). "In conclusion, combination therapy of DPP-4 inhibitor linagliptin and SGLT2 inhibitor empagliflozin increased β-cell mass and enhanced β-cell function in an early phase of diabetes in diabetic db/db mice." (PMID 34373487, 2021). "DPP4 inhibitors are a novel available antihyperglycemic drug approved for treating type 2 diabetes mellitus (T2DM) in clinical practice, decreasing DPP4 enzyme activity and further increasing the concentration of DPP4 substrates." (PMID 34489872, 2021). "DPP4 inhibitors have been approved by the Food and Drug Administration (FDA) for the treatment of type 2 diabetes mellitus." (PMID 34955820, 2021). "Inhibitors of DPP-4 (the enzyme that deactivates GLP-1) and GLP-1 analogs that have functions similar to those of GLP-1 have been commercialized for the treatment of diabetes and have also recently been used for the treatment of obesity." (PMID 33800785, 2021). "Promising diabetes medications were introduced to the market including GLP-1 agonists, DPP-4 inhibitors, and SGLT2 inhibitors aiming to target these complications." (PMID 32190049, 2020). "Clinically, DPP-4 inhibitors, a class of oral hypoglycemics that block DPP-4 activity, increase GLP-1 concentrations and are used to treat type 2 diabetes mellitus." (PMID 33105690, 2020). "Saxagliptin, a dipeptidyl peptidase-4 (DPP-4) inhibitor, prevented vascular remodeling and OS in a genetic model of diabetes." (PMID 32718053, 2020). "Sitagliptin, a DPP-4 inhibitor, has been reported to decrease FABP4 concentration in drug-naïve and sulfonylurea-treated patients with type 2 diabetes mellitus." (PMID 32539832, 2020). "Our study retrospectively analyzed the clinical data of elderly patients with type 2 diabetes mellitus treated with DPP-4 inhibitors, in order to evaluate the hypoglycemic efficacy and safety of liver and kidney of DPP-4 inhibitors in these elderly patients." (PMID 32368255, 2020). "To evaluate the role of CD26/DPP4 inhibition in clinical setting, we conducted a retrospective analysis of patients with advanced airway and colorectal cancers with diabetes who were taking DPP4i." (PMID 32296640, 2020).
diabetes (continued). "Recently, dipeptidyl peptidase-4 (DPP-4) inhibitors and sodium-glucose cotransporter 2 (SGLT2) inhibitors have been very often used in subjects with type 2 diabetes mellitus (T2DM)." (PMID 32337293, 2020). "Dipeptidyl peptidase-4 (DPP-4) inhibition has been shown to increase circulating HSCs in humans, which suggests that DPP-4 dysregulation plays a central role in diabetes mellitus-induced impaired HSC mobilization." (PMID 31575077, 2019). "We then injected our nanocarrier Cas9-RNP complexes directly into type 2 diabetes mellitus (T2DM) db/db mice, which disrupted the expression of DPP-4 gene in T2DM mice with remarkable efficacy." (PMID 30696428, 2019). "Dipeptidyl peptidase-4 (DPP-4) inhibitors and glucagon-like peptide-1 receptor agonists (GLP-1 RAs) are used to treat type 2 diabetes mellitus (T2DM) in adults." (PMID 31870322, 2019). "In addition, cases of noninsulinoma pancreatogenous hypoglycemia due to excessive insulin secretion, regardless of the presence/absence of underlying diabetes mellitus, have been reported, at least partly explaining the episode of hypoglycemia in patients receiving DPP-4 inhibitors alone." (PMID 30815039, 2019). "Sitagliptin, a dipeptidyl peptidase-4 (DPP-4) enzyme inhibitor, is indicated for the management of glycemic control in type 2 diabetes mellitus, together with a controlled diet and physical activity." (PMID 31861192, 2019). "The dipeptidyl peptidase 4 inhibitor vildagliptin (VLD), a widely used anti‐diabetic drug, exerts favourable effects on vascular endothelium in diabetes." (PMID 30444033, 2019). "Human dipeptidyl peptidase-4 (DPP4) is a serine protease, well known FDA-approved therapeutic drug target for regulating blood glucose metabolism and treating diabetes mellitus." (PMID 31661941, 2019). "The expression pattern of CAV1 was similar to that of DPP-4 and integrin β1 (increased by the BSA injection and diabetes and decreased by the TENE treatment)." (PMID 31101909, 2019). "As a consequence, TGR5 agonists have attracted attention as therapeutic candidates for diabetes-based liver fibrosis including NASH, particularly in combination with a DPP-4 inhibitor." (PMID 31561561, 2019). "Dipeptidyl peptidase-4 (DPP-4) inhibitors, a relatively new class of diabetes medications, have been used widely since their approval in the United States in 2006." (PMID 30016946, 2018). "This study aimed to evaluate the effect of sitagliptin, a dipeptidyl peptidase-4 inhibitor, on the longitudinal change in GSM, an index of the tissue characteristics of the carotid wall, in patients with type 2 diabetes mellitus (T2DM)." (PMID 29402270, 2018). "Since its launch in 2006 by Merck, sitagliptin phosphate monohydrate, the first DPP-4 inhibitor (dipeptidyl peptidase 4), has been one of the best-selling orally active and safe agents for the treatment of T2DM (type 2 diabetes mellitus)." (PMID 29899310, 2018). "Major proteins involved in diabetes, such as AMPK, PPARs, dipeptidyl peptidase 4 (DDP-4), and others have been reported to interact with polyphenols, suggesting a potential therapeutic application for natural bioactives in the modulation of metabolic diseases." (PMID 29396566, 2018). "Other hypoglycemic agents, such as biguanides, dipeptidyl peptidase 4 (DPP-4) inhibitors, and thiazolidinediones (TZDs), have also been demonstrated to improve diabetes-related endothelial dysfunction." (PMID 28373902, 2017). "Dipeptidyl peptidase-4 (DPP-4) inhibitors are effective and safe oral antihyperglycemic agents for the treatment of type 2 diabetes mellitus (T2DM)." (PMID 29317794, 2017). "They found that a better response to DPP-4 inhibitors would be expected in patients with T2DM who had higher baseline HbA1c and creatinine levels with shorter duration of diabetes." (PMID 27882332, 2016). "Hence, inhibiting DPP-4 may be a therapeutic target for treating kidney fibrosis in diabetes." (PMID 28058051, 2016).